NSD1 (nuclear receptor binding SET domain protein 1)
Diseases named in the same sentence as NSD1 in open-access papers (continued):
Sharing a sentence is not in itself a finding about the gene and the disease.
cancer (continued). "More recently, many studies show that the NSD1 were overexpressed, amplified or somatically mutated in multiple types of cancer, suggesting their critical role in cancer." (PMID 29156722, 2017). "For example, while mTOR and E2F1 are the top-ranking oncomodules associated to mutations of MLL2 in HNSC, we found that oncomodules in the MEK/AKT1 axis are top-ranking in association to NSD1 mutations in the same cancer type." (PMID 27095575, 2016). "Our pan-cancer regression tree revealed global CGI hypomethylation in samples with mutated NSD1, which came primarily from the HNSC data set." (PMID 25960768, 2015). "The study have demonstrated that NSD1 counteracts Polycomb‐repressive complex 2 (PRC2) through collaboration with SWI/SNF complex, and the study have identified the co‐occurrence of NSD1 inactivation in SWI/SNF‐deficient cancers, which indicates its relevance in vivo." (PMID 39779467, 2025). "Collectively, the majority of studies on NSD1 suggest that NSD1 mutations promote an immune-cold tumor microenvironment, which may be reversed by targeting the altered chromatin landscape in these mutant cancers." (PMID 40586874, 2025). "These bidirectional roles of NSD1 may be influenced by mutation types, co-factor interactions, and chromatin states in a cancer-type-specific manner." (PMID 41301842, 2025). "Two mutations in cancer-related genes were pre-existent in parental HMECs: NSD1 D588G (unknown significance) and KMT2D R5266H (rare germline variant classified as probably benign)." (PMID 38388848, 2024). "NSD1 is a histone methyltransferase, and recent studies demonstrated an association between loss of NSD1 function, in particular by truncating mutations, and a genome-wide hypomethylation in different cancers, including HNSC." (PMID 36980544, 2023). "Interestingly, our results showed a significant increase in NSD1 mutations in the low-methylation groups of several cancer types, in accord with previous results." (PMID 35134107, 2022). "Notably, both, blood samples from individual with SOTOS overgrowth syndrome (carrying germline NSD1 loss of function mutations) as well as NSD1-mutant cancer cells exhibited hypomethylation of intergenic DNA." (PMID 33898929, 2021). "Interestingly, NSD1 mutations showed the most significant association with backbone DNA demethylation not only in HNSCC but also in other cancers." (PMID 34575025, 2021). "The somatic dysregulation of NSD1 is associated with tumorigenesis, suggesting that NSD1 may serve as a prognostic target for the treatment of cancers." (PMID 31727171, 2019). "NSD1 mutations in HPV(+) cancers may also play a prognostic role, although this effect must be examined in a larger cohort." (PMID 31321084, 2019). "Here we have presented evidence that NSD1 also carries germline cancer predisposition variants." (PMID 29973584, 2018). "Since NSD1 is frequently mis-regulated in cancers, it is tempting to speculate that metabolic rewiring could cause epigenomic alterations in favor of cancer malignancy." (PMID 39904567, 2025). "A computational search for cancer predisposition genes based on the Knudson’s two-hit hypothesis using genome data of ~10,000 tumors identified genes including NSD1 that may contribute to cancer through a combination of rare germline variants and somatic loss-of-heterozygosity (LOH)." (PMID 34575025, 2021). "Interestingly, in vitro functional studies performed with human brain and breast cancer cells lines found a potential link of reduced expression or mutations of NSD1 to drug resistance; however, its general significance for cancer therapy remains to be validated." (PMID 34575025, 2021). "In agreement with such a notion, NSD1 was suggested to act as both an oncogene and a tumor suppressor gene in different cancers." (PMID 40118455, 2025). "Mutations in NSD1 and NSD2 are linked to developmental syndromes and cancer, highlighting their critical biological functions." (PMID 40586874, 2025).
cancer (continued). "In summary, we conclude that the NSD1 enzyme is oncogenic and contributes to cancer cell growth in HPV-negative HNSCC via support of the Akt/mTORC1 pathway and regulation of autophagy." (PMID 38346948, 2024). "NSDs activation, including NSD1, NSD2, and NSD3 has been found to be tightly associated with the occurrence and progression of different cancer types." (PMID 39163297, 2024). "A more nuanced understanding of the biological functions of the NSD1 gene will lead to insights into the etiologies of SoS and cancer." (PMID 39336709, 2024). "With the exception of the singular H3K36me3-depositing SETD2, which appears to unambiguously function as a tumor suppressor, the remaining H3K36 methyltransferases (NSD1, NSD2, NSD3, and ASH1L) are all implicated in or associated with various cancers." (PMID 39403928, 2024). "In summary, we conclude that NSD1 enzyme is oncogenic and contributes to cancer cell growth in HPV-negative HNSCC, via support of Akt/mTORC1 pathway and regulation of autophagy." (PMID 37786686, 2023). "We show that mutations of Y1971 and R2017 in NSD1 abrogate catalytic activity indicating that NSD1 can act as a tumor suppressor gene in some tumor types which is in line with its frequent silencing or deletion in cancers." (PMID 37150325, 2023). "In cancer cells, numerous somatic mutations were observed in critical epigenome regulators including the H3K36 dimethyltransferases NSD1 and NSD2." (PMID 37150325, 2023). "This work highlights a previously unsuspected role of NSD1 in control of cell growth and autophagy in cancer." (PMID 37786686, 2023). "Mutated SMARCB1 is unable to bind to NSD1 but binds to PRC2, leading to an increase in H3K27me3 with poor prognosis in cancer patients." (PMID 36589746, 2022). "High NSD1′s hypermethylation level was observed in metastatic kidney tumors and often predicted advanced cancer stage and poor overall patient survival." (PMID 36230787, 2022). "It is worth noting that apart from EZH2, a variety of downstream effectors of NSD1 has been reported in different cancers." (PMID 36230787, 2022). "Of note, we found several mutations in genes identified within the low-methylation group to be useful for classification, including NSD1 (1/10 cancers)." (PMID 35134107, 2022). "Alterations in NSD1′s expression have already shown promise as a prognostic biomarker in various cancers." (PMID 36230787, 2022). "NSD1 has been identified as a biomarker for global epigenetic changes in cancer and based on TCGA data, it was recently suggested as a prognostic biomarker in patients with HPV-negative HNSCC." (PMID 34631566, 2021). "Although selective NSD1-SET inhibitors are highly relevant for aggressive NUP98-NSD1+ pediatric AML, one has to take into consideration that loss-of-function mutations of NSD1 are much more prevalent in human cancers." (PMID 34575025, 2021). "While NSD1 overexpression impaired colony growth in semi-solid medium and proliferation of cancer cells, RNAi-mediated knock-down increased proliferation, suggesting a role of a tumor suppressor." (PMID 34575025, 2021). "In humans, putative loss of function NSD1 mutations characterize developmental syndromes, such as SOTOS, as well as cancer from different organs." (PMID 34575025, 2021). "We noticed that genes encoding chromatin modifiers were often hypermethylated in several cancer types, including the histone methyltransferases KMT2C (11 cancer types) and NSD1 (7 cancer types) and the histone demethylase KDM2B (6 cancer types)." (PMID 34871444, 2021).
cancer (continued). "Third, heterozygous germline point mutations in NSD1 are the molecular correlate for SOTOS, an overgrowth syndrome with learning disabilities and increased cancer risk." (PMID 32533074, 2020). "Second, the CpG island promoter of the NSD1 locus has also been reported to be frequently hyper-methylated in certain human cancers, thereby epigenetically silencing the allele." (PMID 32533074, 2020). "This last result brings new insights regarding the involving of NSD1 in cancer initiation and progression." (PMID 32153656, 2020). "When the analysis focuses on cancer stage, the results of the contingency table imply that in initial stages (stage I) the expression of NSD1 is lower." (PMID 32153656, 2020). "It is probable that the performance of NSD1 in cancer progression is required after the initiation process, and then, its expression increases." (PMID 32153656, 2020). "In respect to genetic alterations found in these genes, for example, it is common that NSD1 is harboured in cancer cells, a translocation in the chromosome 5, resulting in a behaviour similar to oncogenes." (PMID 32153656, 2020). "Alterations in NSD1 expression have already shown promise as a prognostic biomarker in various cancers." (PMID 31321084, 2019). "And NSD1 (which encodes a histone methyltransferase) was associated with a high HypoZ index in HNSC and has also been linked to hypomethylation in cancer." (PMID 29125844, 2017). "Our analysis revealed a particularly striking correlation of the NSD1 subtypes between these two tumor types, postulating NSD1 inactivation as a driver of this novel molecular pan-cancer group." (PMID 29213088, 2017). "Our data suggest that NSD3 is a compelling drug target for cancer and that NSD1/NSD2/NSD3 structural similarity should be used for structure-based drug design to develop a new class of histone methyltransferase inhibitors for cancer." (PMID 24874471, 2014). "This analysis led to discovery that AURKA inhibitors may be effective in cancers where tumour suppressors like FBXW7 or NSD1 are compromised." (PMID 40775769, 2025). "In addition, multiple chromosomal translocations have been identified in the context of NSD1, 2 and 3 with functional roles in cancer." (PMID 40586874, 2025). "While most functional investigations have focused on HNSCC, extending this analysis to other cancer types, particularly those harboring NSD1 alterations could reveal whether this immunosuppressive phenotype is conserved beyond HNSCC." (PMID 40586874, 2025). "However, despite these promising aspects, NSD1 remains a challenging therapeutic target, motivating our exploration of NSD1’s direct targets to uncover new options for cancer therapy." (PMID 38539515, 2024). "However, non-tumorigenic human keratinocytes also have increased sensitivity to DNA-damaging agents after NSD1 depletion, which is suggestive of NSD1 regulation of this process not only in cancer, but also in normal cells." (PMID 38346948, 2024). "Taken together, these data identify positive regulation of Akt/mTORC1 signaling and autophagy as novel NSD1 functions in HNSCC, suggesting that NSD1 may be of value as a therapeutic target in this cancer." (PMID 37786686, 2023). "In addition, many missense variants of NSD1 and NSD2 were observed in various types of cancers like hematological cancers, head and neck squamous cell carcinomas, human brain tumor cell lines, and lung cancers." (PMID 37150325, 2023). "In contrast, NSD1 is best known as the causative gene for the congenital overgrowth disorder SOTOS and is genetically or epigenetically deregulated (either inactivated or overexpressed) in other cancer types." (PMID 37176149, 2023).
cancer (continued). "Besides these global chromatin effects related to HMT activity, it has been demonstrated in other cancer types that NSD1 regulates additional oncogenic signaling pathways, such as Nuclear Factor-kappa B (NF-κB), Wnt/β-catenin, and HIF1α." (PMID 37786686, 2023). "NSD1′s somatic dysregulation, which results from transcriptional silencing associated with CpG island-promoter hypermethylation and translates into reduced H3K36 methylation, has been described in a variety of human cancers." (PMID 36230787, 2022). "As reported, NSD1 is a potential target for cancer diagnosis and treatment." (PMID 35200072, 2022). "Of note, HPV-negative HNSCC with NSD1 mutations were associated with a decreased expression of ERCC5 mRNA levels, and inactivation of ERCC5 has been previously shown to increase sensitivity to cisplatin in a variety of cancers." (PMID 36230787, 2022). "Moreover, somatically acquired alterations are frequently detected in various human cancers, and RNAi-mediated knock-down seems to increase the proliferation of tumor cells, suggesting the role of NSD1 as a tumor suppressor." (PMID 35888078, 2022). "Considering their crucial role in the epigenetic regulation of cancer processes, selective inhibition of the histone methyltransferases NSD1, SETD2 and EZH2 could offer beneficial therapeutic strategies in treating cancer." (PMID 36230787, 2022). "Increased NSD1-SET activity has been implicated particularly in hematological malignancies, whereas loss-of function mutation or impaired expression characterize a wide variety of mostly solid human cancers." (PMID 36230787, 2022). "Notably, interrogation of the cancer cell line encyclopedia (CCLE) indicates that only a very small number (5/1457) of human cancer cell lines completely lost NSD1 expression at the mRNA level." (PMID 34575025, 2021). "Targeted sequencing of a large number of genes associated with hematologic malignancies revealed rare and potentially deleterious NSD1 mutations in AML patients suggesting that not only gain but also loss of NSD1 can contribute to transformation of hematopoietic cells." (PMID 34575025, 2021). "Collectively, increased NSD1-SET activity drives a particular hematological cancer, whereas loss-of function mutation or impaired expression characterize a wide variety of mostly solid human cancers." (PMID 34575025, 2021). "Notably, both blood samples of SOTOS patients and NSD1-mutant cancer cells exhibited hypomethylation of intergenic DNA." (PMID 33235911, 2020). "Recent evidence has indicated that somatic dysregulation of the nuclear receptor binding SET domain-containing protein 1 (NSD1) is associated with the tumorigenesis in HCC, suggesting that NSD1 may serve as a prognostic target for this malignant tumor." (PMID 31727171, 2019). "However, how Wnt10b affects the cancer cellular physiology by NSD1 alteration should be the subject of further investigation." (PMID 31727171, 2019). "Contrary to loss-of-function NSD1 mutations in cancers, which suggest a tumor suppressor function, NSD2 has emerged as an oncogenic gene with elevated expression or hyperactive mutations in multiple human cancers, including colorectal, prostate, and lung cancers." (PMID 37602556, 2023). "Conceptually, inhibiting lysine demethylases (KDMs) specific for H3K36me2, such as FBXL10 and FBXL11, is a potential strategy for treating cancers associated with loss-of-function NSD1 mutations, and inhibiting NSD2 may be effective for NSD2-hyperactive cancers." (PMID 37602556, 2023). "How NSD1 is regulated and functions in cancers is largely unknown." (PMID 36230787, 2022). "Finally, we examine the ongoing efforts to target NSD1 signaling in cancers." (PMID 36230787, 2022). "Therefore, findings in Sotos overgrowth syndrome may serve to better understand NSD1 role in cancer." (PMID 36230787, 2022).
cancer (continued). "In addition, NSD1 is a target of recurrent germline or somatically acquired loss and gain-of-function alterations associated with developmental syndromes (e.g., SOTOS) and various human cancers." (PMID 34575025, 2021). "In other non-neuronal models of cancer, NfKB has been linked to inhibition of nuclear receptor binding SET domain protein 1 (NSD1) and SET domain containing 2 (SetD2), two H3K36 histone methyltransferases, which are linked to longevity, though not general to chromatin silencing." (PMID 30983962, 2019). "To begin exploring the factors underlying the survival differences between patients harboring tumors with wild-type and mutant NSD1, we used Cancerrxgene.org, a database in which > 1000 genetically characterized human cancer cell lines have been screened against a wide range of anti-cancer drugs." (PMID 31321084, 2019). "In colorectal cancer, lysine methylation of the NF-kB subunit p65 at K218 and K221 is reversibly regulated by NSD1 and the lysine demethylase FBXL11, activating NF-kB signaling and promoting cancer cell growth and colony-forming capacity." (PMID 41301842, 2025). "The nuclear receptor-binding SET domain (NSD), a family of histone lysine methyltransferases, including NSD1, NSD2/WHSC1/MMSET, and NSD3/WHSC1L1, have been identified as potential therapeutic targets for cancer." (PMID 39163297, 2024). "Inactivation of NSD2 also engendered increased dependency on its paralog NSD1, which independently maintained AR and MYC hyper-transcriptional programs in cancer cells." (PMID 38464251, 2024). "Why do NSD1 and NSD2, both of which deposite H3K36me2 at intergenic regions, have the opposite roles in cancer?" (PMID 37602556, 2023). "As shown, the frequencies of genetic alterations in NSD1, NSD2, and NSD3 across cancers were 5%, 3%, and 7%, respectively." (PMID 37062069, 2023). "The most prevalent altered cancer-related genes were CTNNB1 (16%) and ZNRF3 (16%), followed by EGFR (11%), JARID2 (11%), KMT2B (11%), KMT2C (11%), NSD1 (11%), PIK3CA (11%), SH2B3 (11%), and UBR5 (11%)." (PMID 38023213, 2023). "While both NSD1 and NSD2 deposit H3K36me2, the roles of NSD1 and NSD2 in cancer appear to be distinct." (PMID 37602556, 2023). "We also noted seven genes marked with “caution” in PeCanPIE showing the truncation close to the C-terminal (CUX1, FLCN, FLG, MSH6, NSD1, PRDM9, and USP6), questioning its functional effects in the cancer context." (PMID 35406420, 2022). "In this approach, some studies have already described important molecular alterations in the NSD1, NSD2 and NSD3 genes and their role in cancer initiation and development." (PMID 32153656, 2020). "We recently identified this ‘NSD1 subtype’ as one of five HNSC DNA methylation subtypes, using data from 528 HNSC patients from The Cancer Genome Atlas (TCGA) study." (PMID 29213088, 2017). "The NSD family of HMTases comprised of three members (NSD1, NSD2/MMSET/WHSC1, and NSD3/WHSC1L) are oncogenes aberrantly expressed in several cancers, suggesting their potential to serve as novel therapeutic targets." (PMID 25494638, 2014). "The NUP98-NSD1 fusion protein is an active H3K36 methylase, suggesting that NSD1 enzymatic activity is a necessary oncogenic driver for this cancer." (PMID 24874471, 2014). "In an analysis of 24 breast tumours, rearrangements were found in known cancer genes including BRAF, PAX3, PAX5, NSD1, PBX1, MSI2 and ETV6, each of which is a partner in a fusion gene in several other human cancers." (PMID 24792170, 2014).